CRB1 (crumbs cell polarity complex component 1)
Diseases named in the same sentence as CRB1 in open-access papers (continued):
Sharing a sentence is not in itself a finding about the gene and the disease.
retinal disease (15 papers, 2007 to 2025). "This work extends the network of apicobasal polarity components that influence CRB1-associated retinal disease and underscores its complexity and interconnectivity with multiple molecules and pathways." (PMID 35675330, 2022). "Most of the disease-associated genes were unique to a single retinal disease, with the exception of Abca4, Nmnat1, Casp3, and Crb1, which were each shared across two diseases." (PMID 31527661, 2019). "Although the CRB1 gene was first linked to retinal disease back in in 1999, it took 16 years to obtain the first in vivo proof-of-concept for CRB1-based gene therapy." (PMID 28424578, 2017). "Recent analyses of mammalian models of CRB1-linked retinal diseases provided key insight into the role of CRB proteins in the retina." (PMID 28424578, 2017). "This work may lead to an improved understanding of the molecular basis of CRB1-associated retinal disease, with possible relevance to diagnostic and therapeutic intervention in humans." (PMID 35675330, 2022). "Thus, CRB1 engages in multiple activities affecting cell and tissue integrity, raising the possibility that the variability of CRB1/Crb1-associated retinal disease arises from the differential disruption of these activities." (PMID 35675330, 2022). "The identification of Arhgef12 and Prkci as Crb1 modifier genes in mice may have relevance to diagnosing and developing treatments for human CRB1-associated retinal disease." (PMID 35675330, 2022). "CRB1 retinopathies are rare inherited retinal diseases, and although our study is amongst the largest longitudinal case series, the sample size remains small, with limitations in statistical power and sample heterogeneity." (PMID 37762234, 2023). "This phenotype with outer retinal abnormalities is similar to CRB1 patient-derived retinal organoids and Crb1 or Crb2 mutant mouse retinal disease models." (PMID 37886604, 2023). "In this study, we reveal novel insights into the molecular pathophysiology of CRB1‐related retinal disease through the integration of in‐house multi‐omics data." (PMID 36656098, 2023). "From Crb2 cKO, Crb1+/−Crb2 cKO and Crb1Crb2 cKO retina studies, the severity of the retinal disease is inversely proportional to the amount of CRB1 and CRB2 proteins which seemed to be critical for the development of the retina." (PMID 24339791, 2013). "Another CRB1 paralog, CRB3, localizes to the Müller glial cells, photoreceptors, rod bipolar cells, and vascular pericytes, but variants in this gene have yet to be linked to retinal disease." (PMID 40590804, 2025). "To investigate whether newly-discovered isoforms can provide insight into gene function, we focused on Crb1, a well-known retinal disease gene." (PMID 32620864, 2020). "One of the main working hypothesis that we draw from our four CRB1-LCA-like models is that CRB2 protein levels may be lower or that a less functional variant is of CRB2 is expressed in CRB1 LCA patients compared to less severe CRB1 retinal diseases." (PMID 31795518, 2019). "Otherwise, the prevalence of CRB1 mutations in the Chinese population with retinal disease was unknown for the lacking of enough samples and this will be a subject of further studies." (PMID 27670293, 2016).
cone-rod dystrophy (14 papers, 2010 to 2025). Inherited retinal dystrophies that belong to the group of pigmentary retinopathies. "A novel bi-allelic missense in the exon 9 of CRB1; c.2936G > A; p.(Gly979Asp) was found to be associated with rod-cone dystrophy (RCD)." (PMID 38622537, 2024). "In this study, a large number of medical records of IRD Brazilian patients were reviewed, where 15 patients with CRB1 mutations were selected, and two of them presented cone-rod dystrophy (CRD)." (PMID 28819299, 2017). "Furthermore, two patients with cone-rod dystrophy due to mutations in CRB1 were reported, supporting previous data, in which mutations in CRB1 can also cause cone-rod dystrophy." (PMID 28819299, 2017). "Our study highlighted a direct relation between phenotype severity and the mutation effect on protein functionality in CRB1 Brazilian patients, contributing to current knowledge about disease-causing variants and supporting the association between the CRB1 gene and cone-rod dystrophy." (PMID 28819299, 2017). "The current results showed clearly that mutations in some genes cause different retinopathies, such as the CRB1 gene that causes EORD, LCA, and RP and the ABCA4 gene that causes cone or cone-rod dystrophy, EORD, and STGD." (PMID 30374144, 2018).
Macular dystrophy (14 papers, 2018 to 2025). Macular dystrophy is a nonspecific term for retinal degeneration, generally confined to the macula, usually presumed of genetic origin. "The described cases reveal a novel genotype–phenotype correlation of the c.2506C>A p.(Pro836Thr) variant of the CRB1 gene with macular dystrophy (MD) and high IOP predisposing the individual to an increased risk of glaucoma." (PMID 40243434, 2025). "Patients with missense variations in the CRB1 gene can develop either early-onset RP or LCA or macular dystrophy." (PMID 37886604, 2023). "Additionally, we observed that the severity of macular dystrophy correlates with the overall estimated CRB1 pathogenicity." (PMID 41373703, 2025). "In this report of four patients with macular dystrophy and history suggestingStargardt-like disease, two patient’s phenotypes were related to AD genes(RIMS1 and CRX) and those of the other twopatients were related to AR genes (CRB1 andRDH12)." (PMID 36995812, 2023). "In this cohort, macular dystrophy and EORD occurs even if the CRB1-B isoform is not impacted by pathogenic CRB1 variants." (PMID 34884448, 2021). "The CRB1 isoform B has no impact on the severity of the phenotype as EORD, RP and macular dystrophy can occur regardless of the level of isoform B." (PMID 34884448, 2021).
autosomal recessive retinitis pigmentosa (8 papers, 2008 to 2023). Autosomal recessive retinitis pigmentosa (RP) is an autosomally recessive inherited retinal dystrophy leading to progressive loss of the photoreceptors and retinal pigment epithelium and resulting in blindness usually after several decades. "Mutations in Crb homolog 1 (CRB1) has been shown to cause autosomal recessive retinitis pigmentosa (arRP) and autosomal Leber congenital amaurosis (arLCA)." (PMID 24260128, 2013). "Mutations in the CRB1 gene cause progressive autosomal-recessive retinitis pigmentosa and LCA." (PMID 24339791, 2013).
hyperopia (7 papers, 2012 to 2025). A refractive error in which rays of light entering the eye parallel to the optic axis are brought to a focus behind the retina, as a result of the eyeball being too short from front to back. "High hyperopia is commonly seen in patients with CRB1 mutations." (PMID 23077403, 2012). "Several genes (e.g., BEST1, CRB1, MFRP, PRSS56 and TMEM98) which have roles in both foetal ocular development and post-natal outer retinal maintenance, can be associated with high hyperopia and short axial length." (PMID 41465105, 2025). "We have defined the diagnostic yield of sequencing the coding variants in PRSS56, MFRP, TMEM98, MYRF, CRB1, and BEST1 in a large cohort of patients with nanophthalmos and high hyperopia." (PMID 33203948, 2020). "Hyperopia is common in some IRDs including AD BEST1-retinopathy, RS1 and some LCA genotypes (in the current cohort: AIPL1, ALMS1, CEP290, CRB1, CRX, TULP1)." (PMID 41465105, 2025). "While six genes have been implicated in this hereditary condition (MFRP, PRSS56, MYRF, TMEM98, CRB1,VMD2/BEST1), the relative contribution of these to nanophthalmos or to less severe high hyperopia (≥ + 5.50 spherical equivalent) has not been fully elucidated." (PMID 33203948, 2020).
nanophthalmos (7 papers, 2015 to 2025). "To date, five genes (i.e., MFRP, TMEM98, PRSS56, BEST1, and CRB1) and two loci have been implicated in familial forms of nanophthalmos." (PMID 29862063, 2018). "Furthermore, some recent reports showed association of mutation in CRB1 with nanophthalmos and retinitis pigmentosa." (PMID 29862063, 2018). "Tests of visual acuity could be affected by rd8 mutations in the Crb1 gene found in B6N mice, although all B6 mice are susceptible to ocular disorders, such as microphthalmia." (PMID 27081652, 2015). "Two additional genes, CRB1 and BEST1 (VMD2), have been implicated in nanophthalmos and have profound roles in photoreceptor and retinal pigment epithelial (RPE) function, respectively." (PMID 29862063, 2018). "The risk of this second vision-threatening pathology, particularly angle closure glaucoma, may be higher than that of the general population (1.1%) in some IRD genotypes (e.g., BEST1, CRB1, MFRP) associated with microphthalmia/nanophthalmos." (PMID 41465105, 2025). "Thus far, genes identified in Mendelian cases of nanophthalmos have different roles in the retina (PRSS56, CRB1) and the retinal pigment epithelium (BEST1/VMD2, MFRP)." (PMID 31048900, 2019).
night blindness (6 papers, 2008 to 2024). Inability to see clearly in dim light. "All patients with CRB1 variants had nystagmus as a first symptom and most of them presented photophobia as well as night blindness." (PMID 36369640, 2023). "Symptoms of night blindness were reported by 11 individuals, including CRB1 or TULP1 mutations (all individuals; three each group), RPGRIP1 or RPE65 mutations (two individuals each) and RDH12 mutations (one individual)." (PMID 29178642, 2017). "Case 17, who had novel mutations in CRB1, had a history of night blindness and diffuse hyperpigmentation in the retina, with vascular attenuation." (PMID 18682808, 2008).
Blindness (5 papers, 2017 to 2025). Blindness is the condition of lacking visual perception defined as a profound reduction in visual perception. "Mutations in the CRB1 gene lead to visual impairment and even complete blindness in individuals with many different clinical IRD phenotypes, including LCA, EORD and RP6, 12–14." (PMID 28819299, 2017). "Interestingly, mutations in human CRB1 result in RP12-asssociated blindness, despite the fact that CRB2 and CRB3 are also expressed in the retina." (PMID 28202468, 2017). "Further molecular and biochemical studies will be critical to elucidate CRB1 function in retinal cells, provide insight into the physiology of vision, and help define the events that lead to blindness." (PMID 41373703, 2025).
early-onset retinal dystrophies (5 papers, 2013 to 2025). "The SP sequences of the CRB1 (early-onset retinal dystrophy), NDP (familial exudative vitreoretinopathy) (FEVR), FZD4 (FEVR), EYS (RP), and RS1 (XLRS) genes were affected." (PMID 36362148, 2022).
keratoconus (5 papers, 2009 to 2026). A degenerative, structural disorder of the eye, characterized by a cone-shaped protrusion of the cornea. "The CRB1 mutations in LCA patients have also been suggested to sensitise patients to keratoconus, a form of corneal dystrophy in which the cornea undergoes progressive thinning." (PMID 31988089, 2020). "This can also be emphasized from the fact that in patients with LCA, mutations in the Crumbs homolog 1 (CRB1) gene were seen to cause keratoconus." (PMID 21365019, 2011). "Likewise, keratoconus occurs at higher frequency in Down syndrome (trisomy 21), and in Leber congenital amaurosis (particularly in those with CRB1 mutations), hinting at genetic pathways (perhaps collagen, extracellular matrix, or developmental pathways) that intersect with KC." (PMID 41595486, 2026). "In one patient (LCA81–1) identified with nonsense RPGRIP1 mutation, the clinical diagnosis indicated a cornea plana (lesser K readings suggesting a flater cornea) in contrast to keratoconus, an associated clinical feature of LCA described usually with AIPL1 and CRB1 mutations." (PMID 24066033, 2013).
retinal telangiectasia (5 papers, 2012 to 2024). "Both arRP- and arLCA-patients that carry CRB1 mutations may show additional specific features in fundus images such as preservation of para-arteriolar retinal pigment epithelium and retinal telangiectasia with exudates (also called Coats-like vasculopathy)." (PMID 25147295, 2015). "Our data supports the view that vascular lesions in patients with Crb1 mutations, that show Coat's-like exudates in the inferior region of the retina, are likely to be more similar to retinal telangiectasia with similar vascular features as observed in this study, than choroidal neovascularisation." (PMID 22545116, 2012). "And more than 150 CRB1 mutations are shown to be associated with specific fundus features other than RP or LCA, such as preserved para-arteriole retinal pigment epithelium (PPRPE) and retinal telangiectasia with exudation (Coats-like exudative vasculopathy)." (PMID 34130719, 2021). "CRB1-RD exhibits unique and diverse features, such as PPRPE, coin-like yellow-white spots, retinal thickening, retinal telangiectasia (coats-like), and intermediate uveitis." (PMID 38466290, 2024).
Usher syndrome (4 papers, 2017 to 2024). A syndromic diseae characterized by the association of sensorineural deafness (usually congenital) with retinitis pigmentosa and progressive vision loss. "The largest homozygous region was about 42 Mb and contained three IRD-associated genes: CRB1, RD3 (retinal degeneration 3; OMIM# 180040), and USH2A (Usher syndrome type 2A; OMIM# 608400)." (PMID 28460491, 2017).
glaucoma (3 papers, 2022 to 2025). Increased pressure in the eyeball due to obstruction of the outflow of aqueous humor. "In a retrospective cohort study, 7 out of 55 patients with CRB1 mutations had associated glaucoma." (PMID 38983543, 2022). "A less common non-retinal association that has been described in CRB1 retinopathies is an increased risk of glaucoma." (PMID 40243434, 2025).
Neurodegeneration (3 papers, 2020 to 2024). Progressive loss of neural cells and tissue. "Finally, we asked whether insight into CRB1 isoforms could be used to improve animal models of CRB1 degenerative disease." (PMID 32620864, 2020).
Retinal dysplasia (3 papers, 2022 to 2023). Abnormal growth and differentiation, structure and appearance of the retina present from birth. "Epistatic analysis revealed a genetic interaction between Arhgef12 and Crb1 alleles that led to enhanced retinal dysplasia, suggesting that both genes participate in the same pathogenic pathway." (PMID 35675330, 2022). "Cx3cr1, Mthfr, and Cygb were identified as modifiers of Crb1rd8 retinal dysplasia, Jak3 as an enhancer of a Crb1rd8-dependent neovascular phenotype, and Crb2 as a modifier of retinal dysplasia due to a Crb1 knock-out allele." (PMID 35675330, 2022). "CRB1 disruption is also associated with outer retinal folds and pseudorosettes (retinal dysplasia) that correspond to light spots observed by fundus examination, and with photoreceptor degeneration in dysplastic regions." (PMID 35675330, 2022). "However, the RP phenotype differs from EOSRD/LCA-associated CRB1-retinopathy, which displays a more severe retinal dysplasia." (PMID 37762234, 2023). "In vertebrate models, mutation or loss of zebrafish (Danio rerio) orthologs of apicobasal polarity proteins EPB41L5 (zebrafish moe), MPP5 (nok), and CRB2 (ome) cause retinal developmental and lamination abnormalities similar to Crb1-associated retinal dysplasia." (PMID 35675330, 2022). "Notably, C57BL/6N mice are known to be homozygous for the rd8 mutation in Crumbs homolog 1 (Crb1) gene, which may lead to severe retinal dysplasia in the inferior retina and other ocular abnormalities." (PMID 35212809, 2022). "Our epistasis analysis demonstrated a genetic interaction between Prkci and Crb1 in retinal dysplasia, consistent with known interactions between PRKCI and CRB1 in apicobasal polarity." (PMID 35675330, 2022). "Deficits in mouse CRB1, CRB2, CRB1 and CRB2 combined, MPP5, and PRKCI have similar effects, supporting the hypothesis that defects in apicobasal polarity cause retinal dysplasia." (PMID 35675330, 2022). "Retinal dysplasia is more severe in Tvrm323 mice, which express variants of two apiocobasal polarity proteins, PRKCI and CRB1, when compared to B6 rd8 mice, in which only CRB1 is disrupted." (PMID 35675330, 2022).
retinoblastoma (3 papers, 2016 to 2024). A malignant tumor that originates in the nuclear layer of the retina. "CRB1 is involved in the development of photoreceptor cells, which are suggested to be the cells of origin of retinoblastoma." (PMID 27115612, 2016). "Possibly, overexpression of CRB1 driven by copy number gains accelerates photoreceptor-derived retinoblastoma." (PMID 27115612, 2016). "Besides the well-established driver genes RB1 (13q-loss) and MYCN (2p-gain) we identified CRB1 and NEK7 (1q-gain), SOX4 (6p-gain) and NUP205 (7q-gain) as novel retinoblastoma driver candidates." (PMID 27115612, 2016). "Besides, CRB1 chromosome 1q gain was identified as potential driver in retinoblastoma progression." (PMID 39695086, 2024).
retinoschisis (3 papers, 2022 to 2025). An inherited or acquired disorder characterized by splitting of the retina into two layers. "In contrast, CRB1‐associated (autosomal recessive) retinoschisis usually presents with foveal‐limited schisis, sometimes accompanied by pigmentary changes or Coats‐like vasculopathy, none of which were observed in this patient." (PMID 41473531, 2025). "We report a long-term observation of a female patient with familial foveal retinoschisis (FFR) caused by CRB1 gene with complex heterozygotic mutation." (PMID 37636578, 2023).
Visual impairment (3 papers, 2016 to 2024). "Rodent (Crb1, Lrat, Mertk, Rpe65, and Rpgrip1), avian (Gucy2D), and canine (Rpe65) models for LCA and profound visual impairment have been successfully corrected employing adeno-associated virus or lentivirus-based gene therapy." (PMID 39055259, 2024). "Variations in the CRB1 gene are a major cause for early onset autosomal recessive RP with patients suffering from visual impairment before their adolescence and for LCA with newborns experiencing severe visual impairment within the first months of life." (PMID 32922261, 2020).
asthma (2 papers, 2013 to 2023). "In contrast to our expectation, 6 asthma SNPs showed nominal association with lower eosinophil counts in the general population (rs1233578 [ZBED9], rs519973 [BCL6], rs7686660 [USP38], rs6691738 [TNFSF4], rs2507978 [HLA‐B], rs3117098 [HCG23]), and 1 SNP in the asthma population (rs2786098 [CRB1])." (PMID 37186423, 2023).
Bull's eye maculopathy (2 papers, 2018 to 2025). Progressive maculopathy characterized by concentric regions of hyper- and hypopigmentation, with an initial foveal sparing and whose appearance is said to resemble the central target of a dart board. "Second, although early macular atrophy is a feature of CRB1-associated LCA, the mildest form of disease appears to spare the foveola, presenting as a bull’s-eye maculopathy (Leeds 1, MEH3)." (PMID 29391521, 2018).
ciliopathy (2 papers, 2017 to 2023). A genetic disorder of the cellular cilia or the cilia anchoring structures, the basal bodies, or of ciliary function. "Our strategy, based on first applying several filters to ciliary variants and using many of the bioinformatics tools available, allowed us to identify causal mutations in BBS2, ALMS1 and CRB1 genes in four families, thus confirming the molecular diagnosis of ciliopathy." (PMID 28800606, 2017).